CDH1 (cadherin 1)
Diseases named in the same sentence as CDH1 in open-access papers (continued):
Sharing a sentence is not in itself a finding about the gene and the disease.
breast carcinoma (continued). "CDH1 pathogenic variants appear only to be associated with lobular breast cancer and not ductal breast cancer or other rare types of breast cancer." (PMID 37347260, 2023). "Hence, 40.9% of the samples derived from patients with primary breast cancer demonstrate CDH1 methylation, resulting in metastasis and poor prognosis." (PMID 36810560, 2023). "PEITC-treated breast cancer cells displayed the reactivation of CDH1 that could be due to the decreased activity of DNMT1, DNMT3a, DNMT3b, HDAC1, and HDAC2." (PMID 36765652, 2023). "In breast cancer models, UGDH knockdown caused increased CDH1 and FN1 expression." (PMID 37858159, 2023). "In breast cancer, a reduction in CDH1 expression can promote metastasis." (PMID 37885030, 2023). "Additionally, somatic CDH1 mutations are present in approximately 50% of sporadic cases of DGC, and loss of E-cadherin is a hallmark of lobular carcinoma in situ (LCIS) and LBC." (PMID 35406381, 2022). "In addition, MUC1-C induces the expression of DNMT1 and DNMT3b in breast cancer and induces the DNA methylation of CDH1 tumor suppressor gene and the induction of E-cadherin expression." (PMID 35978806, 2022). "Findings of this database revealed that at the transcriptional level, CDH1/2/4/6/7/11/12/13/15/22/23/24 were overexpressed in breast cancer samples compared to normal tissues, while transcriptional levels of CDH1/3/5/8/9/10/16/17/18/19/20/26/28 were downregulated compared to normal tissues." (PMID 36315446, 2022). "This means that the published CDH1 methylation data are contaminated to an unknown extent by false-positive calls due to leukocyte infiltrates in primary breast cancer specimens." (PMID 36139537, 2022). "Instead, a critical overview of the history of CDH1 gene methylation in human breast cancer with a strong focus on the methodology used is provided, which cites all relevant studies published so far with a thorough discussion of the methodological reasons for contradictory results." (PMID 36139537, 2022). "Thus, the frequencies of CDH1 and BRCA1 mutations were slightly higher than in larger breast cancer cohorts, probably due to random variation within our sample set." (PMID 35948919, 2022). "Although further evidence of clinical correlations for validation in the future should be determined to support our hypothesis, CDH1/2/4/11/12/13 are expected to be potential biomarkers for breast cancer progression and metastasis." (PMID 36315446, 2022). "However, over more than two decades of research, contradictory results concerning CDH1 gene methylation in human breast cancer accumulated." (PMID 36139537, 2022). "Out of 99 archival primary breast cancer specimens, 2 were scored as “CDH1 methylated” (2%)." (PMID 36139537, 2022). "Loss of Cadherin 1 due to its hypermethylation via DNA methylation and trimethylation of H3K27 has been reported during metastasis, where it is important to note that Cadherin 1 is one of the key genes that inhibits metastasis and progression of breast cancer cells." (PMID 36185256, 2022). "We concluded that CDH1/2/4/11/12/13 may be crucial for breast cancer tumorigenesis, providing novel insights into developing detection biomarkers or targeted therapies for breast cancer." (PMID 36315446, 2022). "Several studies have reported the association for the diffuse gastric cancer predisposition gene, CDH1, in lobular, rather than ductal breast cancer." (PMID 33763779, 2022).
breast carcinoma (continued). "By analyzing the increasing number of samples and employing a more sophisticated quantitative high-resolution detection methodology for invasive lobular breast cancer, the most frequent special type of breast cancer, the frequency and the level of CDH1 gene methylation approached nearly zero." (PMID 36139537, 2022). "Some genes associated with cell adhesion were analyzed from this radiation- and estrogen-induced experimental breast cancer model, including E-cadherin gene CDH1, DSC3, GJA1, the Integrin alpha 6 gene ITGA6, the Integrin beta 6 gene ITGB6, the Keratin genes KRT14, KRT16, KRT17, KRT6B, and LAMB3." (PMID 36293530, 2022). "Furthermore, breast cancer subtype analysis showed a significant difference in CDH1 expression between tumors and adjacent normal tissues." (PMID 36293530, 2022). "Fgfr2ΔE18 variants rapidly induced mammary tumours regardless of Cdh1 mutation status, and progressive truncation of Fgfr2-E18 gradually decreased tumour onset." (PMID 35948633, 2022). "In addition, pathogenic variants of PTEN (5 cases), CDH1 (1 case), and STK11 (1 case and 1 control) were too rare to estimate their risks of breast cancer in Chinese women." (PMID 34606182, 2021). "And it promoted the transcriptional repression activity of SNAI1 on CDH1 in breast cancer cells." (PMID 34718323, 2021). "Indeed, other mechanisms for the reduced expression or function of E-cadherin, such as transcriptional downregulation, promoter methylation of CDH1, and post-translational modifications of E-cadherin, have been detected in breast cancer." (PMID 33808143, 2021). "Among non-gastric tumors, our results show that CDH1 mutations are most frequently identified in breast cancer." (PMID 34066044, 2021). "Furthermore, the expression of VEGF-B was upregulated (log FC = 2.6, p = 0.02) in III stage (≥5 cm) mammary carcinomas (n = 24), while the expression of CDH1 was downregulated (log FC = 3.06, p = 0.032)." (PMID 34679042, 2021). "We did though confirm an increased risk in lobular breast cancer (1.7-fold), but not ductal, consistent with the literature for CDH1 patients." (PMID 34073553, 2021). "Furthermore, estrogen-activated ERα has the potential to repress CDH1 gene by binding to the estrogen response element in the promoter region of this gene in breast cancer cells." (PMID 35178360, 2021). "Notably, our data also indicate that an increase in RNF8 and SNAI1 mRNA levels and a decrease in CDH1 mRNA were observed in malignant subtypes of breast cancer, i.e., TNBC patients." (PMID 34357122, 2021). "In the glioma families carrying deactivating CDH1 germline variants here, we observed no cases of gastric or breast cancer." (PMID 33929593, 2021). "Notably, pathogenic germline variants of PTEN, CDH1, and STK11 were extremely rare in Chinese breast cancer patients or controls." (PMID 34606182, 2021). "Somatic inactivation of Cdh1/E-cadherin alone does not predispose mice to mammary tumors in conditional knockout GEM models." (PMID 34359596, 2021). "This method was successfully used to downregulate CDH1 expression in breast cancer cells." (PMID 32722129, 2020). "The P-value is 0.05, and although the results of statistical testing are not very significant, there may be a certain relationship between CDH1 and breast cancer." (PMID 33304391, 2020). "Some rare breast cancers have CDH1 alterations and exhibit IDC morphology." (PMID 32210163, 2020).
breast carcinoma (continued). "· CDH1 and Breast Carcinoma showed 390 peer-reviewed PubMed articles." (PMID 33062523, 2020). "Thus, recruitment of PRC2 to the CDH1 gene, which encodes for E-cadherin, is one mechanism used by EMT transcription factors, in particular Snail1, to induce EMT in pancreatic, gastric, and breast cancer." (PMID 33003334, 2020). "Similarly, STAT3 inhibition diminished the mammary carcinoma incidence and decreased the tumor size and aggressiveness; also, minor ObR expression and high levels of miR-200c and Cdh1 were observed in tumor tissue." (PMID 33334030, 2020). "They observed that 94% of ductal breast cancers were methylated at the CDH1 promoter." (PMID 32301282, 2020). "Molecular variables such as CDH1 alterations may be crucial to predict the survival of breast cancer patients." (PMID 32301282, 2020). "In addition, ectopic HMGA2 expression also remodels chromatin in mammary tumor and breast cancer to a closed conformation at the Cdh1 locus by hypermethylation governed by HMGA2 interaction with DNA methyltransferases (DNMT3A)." (PMID 32365712, 2020). "This truncated CDH1 gene transcript was recently found in breast cancer cells." (PMID 31781079, 2019). "Although CDH1 translation was affected by TRERNA1 in breast cancer, it is still unclear whether metastasis‐related genes including CDH1 are regulated by TRERNA1 at the transcriptional level." (PMID 31012192, 2019). "The long SENP7 transcript has been reported to promote epithelial–mesenchymal transition and decrease the cell adhesion molecule E-cadherin (CDH1) in breast cancer cell line, which could lead to the metastasis of the disease." (PMID 31318878, 2019). "Notably, although in breast cancer cells Cdh1 exhibited an elevated protein abundance, APCCdh1 substrates were also stabilized, indicating an inactive Cdh1 population in breast cancer cells." (PMID 31420536, 2019). "Given a tumor suppressor role for Cdh1 in breast cancer cells, our findings indicate that Cdh1 N-terminal phosphorylation could be a therapeutic target for breast cancers." (PMID 31420536, 2019). "Moreover, miR-9, which is directly bound and upregulated by MYC and MYCN in breast cancer cells, directly targets CDH1, leading to increased cell motility and invasiveness." (PMID 31208279, 2019). "Elevated SIRT1 deacetylase modulate the nuclear localization of FOXO1, an apoptosis associated EMT-TF and deacetylate the acetylated DNMT1 thus inhibition of SIRT1 enhance the DNMT1-mediated silencing of ER-α and CDH1 reflecting mesenchymal acquisition in MDA-MB-231 breast cancer cells." (PMID 35582717, 2019). "The lack of data about the risk of developing breast cancer in CDH1 mutation carriers brings risk-reducing surgery currently under discussion." (PMID 31028995, 2019). "Several frequently mutated genes in breast cancer, such as CDH1, GATA3, and MAP3K1, were not mutated in any MPA/DMBA-induced tumors." (PMID 31366361, 2019). "A study of breast cancer showed that miR-100 could induce the EMT process by regulating the expression of CDH1 (cadherin 1) through SMARCA5." (PMID 31885571, 2019).
breast carcinoma (continued). "The findings of this study indicate that common genetic variations in the XRCC2, PHB, CDH1 and ATM genes, respectively may influence susceptibility to breast cancer among Sri Lankan postmenopausal women." (PMID 29433565, 2018). "Finally, among the breast cancer predisposition genes with moderate/high-penetrance, seven genes (BMPR1A, PTEN, CDH1, NF1, RAD51C, BRIP1, and CHEK2) were replicated for Korean BRCAX (eight for Asian and 15 genes for European high-risk breast cancers)." (PMID 30323354, 2018). "Indeed, suppression of CDH1 expression forces epithelial to mesenchymal transition and imparts a cancer stem cell-like phenotype to human breast cancer cells." (PMID 29735912, 2018). "Furthermore, to corroborate the involvement of FFAR2 in the regulation of E-cadherin expression, we evaluated the correlation between FFAR2 and CDH1 mRNA levels in breast tumors and breast cancer cell lines." (PMID 29049318, 2017). "Actually, we found CDH1 was low expressed in TNBC than other breast cancers in a TCGA cohort." (PMID 28392805, 2017). "In addition, we pre-treated MDA-MB-231 breast cancer cells, which also harbor a hyper-methylated CDH1 promoter, with ML327 followed by TRAIL and demonstrated increased percentage of cells in the Sub G0 cell population as compared to vehicle pre-treated cells." (PMID 29254146, 2017). "Here, we wanted to determine whether the expression of other CDHs is altered in breast cancer, especially in TNBC since CDH1 is mostly downregulated or mutated in TNBC." (PMID 28392805, 2017). "There is paucity of studies with regard to -160C/A CDH1 SNP in breast cancer and there is no other study about association of this SNP with risk of BC in Iranian population." (PMID 29285016, 2017). "Compared to the other anatomic sites, and taking available sample sizes into account, mutations were more prevalent for CDH1 in breast cancer and for CTNNB1 in endometrial cancer, though still not a large proportion of carcinomas at these sites." (PMID 29156750, 2017). "However, CDH1 was low expressed in TNBC, and CDH1 alteration events were mutually exclusive with high-level alterations (amplification or upregulation) of most of SC-TFs used in this study in breast cancers." (PMID 28392805, 2017). "The study based on TCGA breast cancer sequencing data had also demonstrated that most of the remaining ILC without a CDH1 mutation also harbor various E-cadherin gene abnormalities in their transcriptional and/or translational pathways." (PMID 27811364, 2016). "Univariate and multivariate analyses were used to evaluate whether the CDH1 SNPs and the clinicopathological characteristics were independent prognostic factors of breast cancer patients." (PMID 27852262, 2016).
breast carcinoma (continued). "Conversely, some recent studies showed that metastatic breast cancer cells retain the expression of epithelial marker genes such as CDH1, KRT14 and JUP, which could contributed to generation of cancer cell clusters at distant organs of metastatic foci." (PMID 27258152, 2016). "The proband from the second family presents with breast cancer and carries a previously reported pathogenic CDH1 mutation, but also reports no family history of diffuse gastric cancer." (PMID 27064202, 2016). "Moreover, the analyses revealed a mixed epithelial (EGFR+) and mesenchymal (CDH1 null) phenotype for the HBCx-60 (established from metaplastic breast cancer with a spindle cell component)." (PMID 27374081, 2016). "Thus, we were interested in resolving the controversial question regarding the significance of CDH1 -160C/A in breast cancer pathogenesis." (PMID 27349965, 2016). "In further support of this hypothesis, we found that depleting endogenous Cdh1 in MDA-MB-231 breast cancer cells led to downregulation of PTEN and subsequent elevation of Akt activity as demonstrated by an increase in pS473-Akt." (PMID 27462441, 2016). "This study aims to investigate whether the germline variants in CDH1 and CTNNB1 would affect breast cancer susceptibility and patients’ prognosis among Chinese Han women using a haplotype-based association analysis." (PMID 26285011, 2015). "Genetic risk factors vary depending on breast cancer histology, and CDH1 proves that genes involved in susceptibility to ILC do not have to be involved in IDC susceptibility." (PMID 25848941, 2015). "The Cdh1 promoter is often silenced via DNA hypermethylation in breast cancers and during EMT." (PMID 25492890, 2015). "CDH1 inactivation is mutually exclusive to PTK2 activation in breast cancer (p-value = 0.001)." (PMID 26427375, 2015). "The CDH1 gene appears to be rare in Chinese with breast cancer." (PMID 25927356, 2015). "Indeed, there were seven cases of breast cancers in these 11 CDH1 families, some of them at an early age, and histology, when documented, was systematically of the lobular type." (PMID 25848941, 2015). "In addition, a previous study has shown that miR-9, which is directly bound and upregulated by MYC and MYCN in breast cancer cells, directly targets CDH1, leading to increased cell motility and invasiveness." (PMID 24520301, 2014). "Consequently, overexpression of KLF4 in the metastatic MDA-MB-231 breast cancer cell line dramatically increased CDH1 and KRT18 expression, indicating the restoration of an epithelial phenotype and loss of metastasis." (PMID 24429391, 2014). "The CDH1 rs16958383 has been found to have a borderline association with breast cancer in premenopausal, but not postmenopausal, women." (PMID 24838934, 2014). "miR-10b has been found to modulate breast cancer metastasis by targeting CDH1 and may be a useful biomarker of advanced progression and metastasis of breast cancer." (PMID 24520301, 2014).